IGF1 (insulin like growth factor 1)
Diseases named in the same sentence as IGF1 in open-access papers (continued):
Sharing a sentence is not in itself a finding about the gene and the disease.
type 2 diabetes (continued). "In agreement with data from STZ-diabetic rats, the level of endogenous IGF-1 protein was significantly (P < 0.05) lower in DRG from two models of type 2 diabetes, db/db mice and ZDF rats, compared to their control counterparts." (PMID 35298717, 2022). "The consumption of a high DAL diet abundant in protein was found to significantly increase IGF‐1 levels in patients with type 2 diabetes." (PMID 36054595, 2022). "Especially when serum insulin levels are high, as in obese patients with type 2 diabetes, IGF-1 (insulin-like growth factor) receptors are now thought to mediate main proliferative effects." (PMID 36291064, 2022). "Type 2 diabetes leads to increased levels of insulin-like growth factor-1 (IGF-1) and blood glucose." (PMID 35612669, 2022). "The included variables were age at diagnosis, gender, basal GH, basal ULN_IGF-1, BMI, maximum tumor diameter, extrasellar extension, and type 2 diabetes." (PMID 36187107, 2022). "Impaired insulin secretion due to type 1 diabetes lowers serum IGF-1 levels, and improves glycemic control in patients with type 2 diabetes leads to increased IGF-1 levels." (PMID 35370981, 2022). "First, this study found that knockdown of both G6PC and IGF1 improved transplant resistance of stem cells derived from patients with type II diabetes." (PMID 34205470, 2021). "A decrease of IGF-1 and an increase of IGFBP1 was moreover associated with increased risk of developing cardiac failure in older people with type 2 diabetes." (PMID 33686453, 2021). "We, therefore, evaluated the effects of animal versus plant protein-enriched diets (30% protein, 40% carbohydrates, 30% fat) in older patients with type 2 diabetes on circulating IGF-1, IGFBP1 and IGFBP2 levels." (PMID 33686453, 2021). "We showed that, consistent with our preclinical studies, SVECs from humans with type 2 diabetes and advanced atherosclerosis have blunted serine phosphorylation of eNOS in response to both insulin and IGF-1." (PMID 34420367, 2021). "It is also reported that the expression of IGF-1 was significantly decreased in patients with type 1 and type 2 diabetes." (PMID 33867995, 2021). "This notwithstanding, we demonstrate here for the first time that type 2 diabetes in humans is accompanied by both insulin and IGF-1 resistance at the level of the endothelium, providing a conceptual framework for the present study." (PMID 34420367, 2021). "ECs from patients with type 2 diabetes are resistant to both insulin- and IGF-1–mediated eNOS phosphorylation." (PMID 34420367, 2021). "Type 2 diabetes is characterized by an inability of both insulin and IGF-1 (insulin-like growth factor-1) to appropriately activate their intracellular signaling networks in the endothelium and other tissues." (PMID 34420367, 2021). "For example, PR3 is suggested to directly link inflammation to type 2 diabetes through the downregulation of insulin-like growth factor-1/IGFBP3." (PMID 31935243, 2020). "The OR (95% CI) per SD increase in genetically predicted IGF-1 levels was 1.14 (1.05, 1.24) for type 2 diabetes and 1.09 (1.02, 1.16) for coronary artery disease." (PMID 32548700, 2020). "The OR (95% CI) per SD increment in IGF-1 level was 1.14 (1.05, 1.24) for type 2 diabetes and 1.09 (1.02, 1.16) for coronary artery disease." (PMID 32548700, 2020). "IGF1 P1 promoter methylation levels were increased in type 2 diabetes patients compared with normal glucose tolerance subjects, while serum IGF1 levels were lower in type 2 diabetes." (PMID 32678007, 2020). "A survey of type 2 diabetic patients showed that serum IGF-1 and other components were involved in the inflammatory process of diabetic nephropathy through vascular endothelial injury and inhibition of neovascularization." (PMID 31077177, 2019). "The results showed that endogenous insulin/IGF-1 accelerates colon tumor growth in a mouse type 2 diabetes model." (PMID 26901856, 2016).
type 2 diabetes (continued). "Recently, it was shown that cardiomyocytes mediate anti-angiogenic effects in type 2 diabetic rats via the exosomal transfer of miR-320 into endothelial cells where its angiogenesis-related target genes (IGF-1, Hsp20 and Ets2) were down-regulated." (PMID 26930277, 2016). "It has been shown that exogenous administration of IGF1 to type 2 diabetes patients can improve insulin sensitivity; therefore, a direct effect is possible." (PMID 25722973, 2015). "IGF-1 has been shown to increase insulin sensitivity and improve glycemic control in patients with type 2 diabetes." (PMID 23383064, 2013). "In acromegalic patients there is excess of growth hormone and consequently IGF-1 excess, and this results in glucose intolerance and type II diabetes." (PMID 23533949, 2013). "Elevated serum insulin-like growth factor 1(IGF-1), reduced testosterone and human growth hormone and premature type II Diabetes Mellitus suggest an hastened decline in neuro-endocrine dysfunction." (PMID 22815920, 2012). "Estrogen also inhibits production of insulin-like growth factor-1 (IGF-1) and low levels of IGF-1 are associated with an increased risk type 2 diabetes." (PMID 22448212, 2012). "IGF-1 (insulinlike growth factor-1) has a function similar to insulin, and it can also improve blood sugar profiles in type 2 diabetics." (PMID 21689475, 2011). "study indicated that miR-335-3p could improve the type II diabetes mellitus by regulating macrophage polarization through targeting the IGF-1." (PMID 39754051, 2025). "This suggests the potential role of IGF-1 as a novel therapeutic target, also in combination with insulin, in therapeutic strategies to repair impaired glucose metabolism in the treatment of dementia in sporadic Alzheimer’s disease and type 2 diabetes." (PMID 40283962, 2025). "Clinical investigations indicate that IGF-1 may protect against development of glucose intolerance or type-2 diabetes and subcutaneous IGF-1 treatment reduces insulin required to maintain normoglycemia in type-1 diabetes patients." (PMID 35989990, 2022). "Serum levels of IGF1 were reported to be elevated in type II diabetes mellitus (T2DM)." (PMID 35741102, 2022). "Altogether, these results suggest that IGF-1 could be more useful for predicting type 2 diabetes than long-term cardiovascular outcomes in hyperglycemic ACS patients." (PMID 34851758, 2021). "Moreover, we clarified the prevalence of type 2 diabetes before onset, statistical analysis, prognosis, and specific effects of IGF-1." (PMID 32337291, 2020). "Notably, several age-downregulated genes, such as Plxdc2, Igf1, Igf2bp3, and Igf1r, and upregulated genes, such as Adam19 and Tmem163, have been linked to IGF signaling or type 2 diabetes." (PMID 30180872, 2018). "Recent studies have suggested that alcohol-induced changes in the circulating levels of IGF-1 and GH might contribute to the alcohol-mediated development of glucose intolerance and type 2 diabetes." (PMID 28988577, 2017). "Our study provides relevant information on levels of serum 25(OH)VD3, HIF-1α, VEGF, vWf, and IGF-1 in a large-scale cohort to further understand the law of their changes and to clarify their correlation in type 2 diabetes patients with different urine albumin creatinine ratio." (PMID 27069929, 2016). "Type 2 diabetes negatively affects skeletal muscle function and mass, which may be a result of increased miR-133a expression together with low Igf-1 in skeletal muscle." (PMID 27445979, 2016). "In conclusion, increased serum HIF-1α, VEGF, vWf, and IGF-1 and decreased serum 25(OH)VD3 may have an association with diabetic renal damage in type 2 diabetes patients." (PMID 27069929, 2016). "Targeting these key players may hold promise for the development of novel therapies for age-related pathologies with aberrant IGF-1 signalling such as type 2 diabetes, skin atrophy, osteoporosis, impaired wound healing, and neurodegenerative disease." (PMID 25520316, 2015).
type 2 diabetes (continued). "Herein, we hypothesized that there is a therapeutic potential of IGF-1 administration in neurodegenerative diseases such as type 2 diabetes." (PMID 24696681, 2014). "Most type II diabetics have elevated insulin and insulin-like growth factor (IGF)-1 levels at baseline, which are mitogenic to tumor cells via activation of downstream signaling cascades that mediate proliferation, migration/invasion, angiogenesis, and treatment resistance." (PMID 24133632, 2013). "Although the associations between the SNPs in MADD, ADRA2A, C2CD4B, IGF1, IRS1and FADS1 with fasting glucose or type 2 diabetes were directionally consistent with those observed for white Europeans and of similar magnitude to that observed in the previous GWAS, none reached nominal significance." (PMID 21747906, 2011). "Some researchers established a Type 2 Diabetes Mellitus model for colorectal cancer, and revealed that the activation of ERK1/2 and JNK signaling by insulin and IGF-1, at least in part, is responsible for the development of colon cancer with T2DM." (PMID 40406485, 2025). "Additionally, metformin, commonly used in the treatment of type 2 diabetes, has been studied for its anti-cancer properties due to its ability to inhibit metabolic pathways that intersect with IGF-1 signaling, making it a candidate for combination therapy in cancer treatments." (PMID 39596005, 2024). "Variants in other interaction partners of NCOA3 including insulin growth factor 1 (IGF1 rs5742643), HNF1 homeobox A (HNF1A rs1800574 and rs56348580), and IQ motif containing K (IQCK rs7185636) were associated with systolic blood pressure, type 2 diabetes, or Alzheimer’s disease, respectively." (PMID 34864818, 2021). "In obesity and type 2 diabetes mellitus (T2DM), IGF-1 can induce cardiomyocytes hypertrophy through overactivity of growth pathway." (PMID 32290181, 2020). "Meanwhile, the increased IGF-1 level in serum may reduce the risk of non-vertebral fractures in patients with type 2 diabetes." (PMID 30459613, 2018). "In addition, a deregulated manner of the IGF-1/Akt/mammalian target of rapamycin (mTOR) participating in exosome secretion could be happened during the onset of type 2 diabetes." (PMID 30127829, 2018). "The selected cortical bone from posterior cortex region of tibia was of our specific interest, because in addition to the IGF1-dependent regulation of cortical bone size, cortex makes up 80% of the skeleton and cortical bone is preferentially compromised in diabetic patients (type 2 diabetes)." (PMID 25629402, 2015). "Previous diet intervention studies in patients with type 2 diabetes revealed reduced BMI, blood pressure, fasting glucose, total and low density cholesterol, CRP and IGF-1 levels in a cohort of 100 participants, particularly in those at risk for disease." (PMID 38600065, 2024). "The increase of IGF-1 inhibits the occurrence of bone resorption, The bone resorption marker TRACP-5b was significantly reduced, preventing osteoporosis in patients with type 2 diabetes." (PMID 35571731, 2022). "In patients with type 2 diabetes, the GH/IGF-1 axis shows an increase in GH and a decrease in IGF-1." (PMID 34479652, 2021). "It is known that growth factors such as insulin, IGF-1 and HGF support beta cell growth and survival, but in people with type 2 diabetes the destructive effects of metabolic stress predominate and beta cell death or dysfunction occurs." (PMID 32978479, 2020). "In patients with Type 2 Diabetes who had low levels of Insulin-like Growth Factor (IGF-1), Zinc supplementation significantly increased IGF-1 concentrations." (PMID 22515411, 2012). "Since some lean patients with type 2 diabetes may be more insulin sensitive, PI3K-Akt-mTOR pathway could be further stimulated by insulin and IGF-1, compared to in obese patients." (PMID 35351050, 2022). "Elevated levels of IGF-1 are not a characteristic of type 2 diabetes, IGF-1 has been suggested to be protective against type 2 diabetes instead." (PMID 35615721, 2022).
type 2 diabetes (continued). "In the LEGUAN study, we addressed the question whether the protein source in a high-protein diet, animal- vs. plant-based protein, is a relevant determinant of circulating IGF-1, IGFBP1 and 2 levels in participants with type 2 diabetes." (PMID 33686453, 2021). "The combination of insulin and IGF-1 resistance in skeletal muscle in mice, due to expression of a mIGF-1R (mouse IGF-1 receptor), which forms nonfunctioning hybrids with native IR (insulin receptor) and IGF-1Rs (IGF-1 receptors), leads to type 2 diabetes." (PMID 34420367, 2021). "IGF-1 carries potential for predicting type 2 diabetes, rather than long-term cardiovascular outcomes and post-ACS myocardial infarct size and dysfunction, in hyperglycemic ACS patients." (PMID 34851758, 2021). "In a rat model of type 2 diabetes (i.e., the type-2 diabetic Otsuka Long-Evans Tokushima Fatty rat model), alcohol administration significantly decreased IGF-1 serum levels and increased GH serum levels compared with nondiabetic control rats." (PMID 28988577, 2017). "Finally, when compared to untreated type 2 diabetes patients, the metformin-treated diabetic patients showed increased IGFBP-2 levels with diminished serum IGF-1 levels." (PMID 27009398, 2016). "Moreover, PRTN3 has been proposed as an inflammatory enzyme able to digest insulin-like growth factor 1 (IGF-1) and the insulin-like growth factor-binding protein-3 (IGFBP3) and promote glomerular inflammation in type 2 diabetes." (PMID 25874235, 2015). "Thus, we were able to confirm decreased levels of IGF-1 and increased levels of IGFBP-1 in type 2 diabetes patients with nephropathy." (PMID 22400116, 2012). "It is possible that an increase in IGFBP2 concentrations occurs in type 2 diabetes followed by an increase in local IGF1 and IGF2 concentrations in the renal glomerulus, very similar to the hypothesis postulated for IGF1 and IGFBP1 interaction in nephropathy." (PMID 23781310, 2012). "The direction of associations for loci ADRA2A, IGF1 and IRS1 were consistent to those observed in the previous GWAS, however none of the remaining loci were associated with type 2 diabetes (P≥0.21), IFG (P≥0.10) or combined IFG/type 2 diabetes (P≥0.22)." (PMID 21747906, 2011). "SNPs in or near MADD, ADRA2A, PROX1, FADS1, C2CD4B, IGF1, and IRS1 did not exhibit significant associations with type 2 diabetes or related glycemic traits (P≥0.10)." (PMID 21747906, 2011). "Indeed, functional inactivation of the IGF-1 and insulin receptors in skeletal muscle (MKR mice) leads to type 2 diabetes phenotype." (PMID 17987120, 2007). "A limitation of this study is that the genetic instrument was for total IGF-1 levels rather than the free and bioavailable IGF-1 fraction, which may be more strongly associated with type 2 diabetes and cardiovascular diseases." (PMID 32548700, 2020). "Taken together, mice with a genetically engineered IGF1 deletion have increased the capacity of researchers not only to understand how type II diabetes contributes to tumor growth, but also how this complex multifactorial disease impacts the tumor microenvironment and promotes metastasis." (PMID 30567377, 2018). "Another study involving type 2 diabetic patients showed a significant correlation between circulating VEGF-A and serum levels of hypoxia-inducible factor-1α (HIF-1α) and insulin-like growth factor-1 (IGF-1), which are considered to be involved in the pathogenesis of diabetic nephropathy." (PMID 28835895, 2017). "For these studies, nondiabetic control and type 2 diabetic ob/ob mice were challenged with an intrathecal injection of insulin or insulin-like growth factor 1 (IGF-1) and downstream signaling was evaluated in the DRG and sciatic nerve using Western blot analysis." (PMID 24252636, 2013).
type 2 diabetes (continued). "In this trial of patients with type 2 diabetes and CKD who were randomized to receive canagliflozin or placebo, we showed that baseline IGF-1 levels and IGF-1/IGFBP-3 ratio (but not IGFBP-3 concentrations) were associated with cardio-renal outcomes." (PMID 37438734, 2023). "Insulin and IGF-1 stimulated Akt phosphorylation were similar when comparing SVEC from patients with and without type 2 diabetes." (PMID 34420367, 2021). "As we demonstrated in preclinical models, insulin and IGF-1 stimulated eNOS phosphorylation were blunted in SVEC from patients experiencing type 2 diabetes, compared with patients without type 2 diabetes." (PMID 34420367, 2021). "As far as we know, two previous studies in humans, with small sample size (n = 39–40), examined protein or gene expression of the IGF1, IGF2, IGFBP3, INSR, IGF1R and downstream targets IRS1, IRS2 and mTOR in women with or without type 2 diabetes." (PMID 29486734, 2018).